MALAT1 (metastasis associated lung adenocarcinoma transcript 1)
Diseases named in the same sentence as MALAT1 in open-access papers (continued):
Sharing a sentence is not in itself a finding about the gene and the disease.
tumor (continued). "In the blocked group, the unlabelled MALAT1 ASO reduced the overall 5’(Cy5.5)-MALAT1 ASO probe uptake, which is significantly lower in the tumour (p=0.002), suggesting the targeted specificity of the 5’(Cy5.5)-MALAT1 ASO probe." (PMID 29156758, 2017). "For example, lncRNA BANCR functions as a tumor suppressor in NSCLC, whereas HOTAIR and MALAT1 promote oncogenic functions in NSCLC." (PMID 29228680, 2017). "The results showed MALAT1 was overexpressed in PCa tissues and high expression of MALAT1 had close relationships with high Gleason score, prostate specific antigen (PSA), and tumor-node-metastasis (TNM) stage." (PMID 27143813, 2016). "Quantitative Real Time PCR (qRT-PCR) revealed that, in the unstimulated condition, tumor cells expressed variable levels of HOTAIR, MALAT1 and ANRIL." (PMID 27922078, 2016). "Moreover, MALAT1 could be involved in EMT process to promote tumor metastasis." (PMID 27143813, 2016). "The capacities of MALAT1 and HIF-2α to promote tumor growth are validated in mouse xenograft models." (PMID 26735578, 2016). "Overexpression of MALAT1 in mice using a lncRNA gain-of-function system promoted CRC cell proliferation, invasion, and migration, and enhanced tumor growth and metastasis after implantation." (PMID 27686732, 2016). "MALAT1 affected cell growth through regulation of the ATM-CHK2 pathway, allowing gene amplification in the tumor progression period." (PMID 27686732, 2016). "The overexpression of MALAT1 promoted CRC cell proliferation, invasion, and migration in vitro and tumor growth and metastasis in vivo." (PMID 26307974, 2015). "First, we defined the MALAT1 expression status in all the 54 OSCC samples and 10 non-tumor normal oral mucosa samples." (PMID 26522444, 2015). "Regarding the underlying molecular mechanisms, MALAT1 showed the ability to competitively bind to the tumor suppressor gene SFPQ and release the proto-oncogene PTBP2 from the SFPQ/PTBP2 complex, while the increased SFPQ-detached PTBP2 could promote tumor growth and migration." (PMID 26307974, 2015). "Among them, HOTAIR, PVT1, H19, MALAT1, GHET1 and HULC were significantly higher in tumor tissues compared with control tissues." (PMID 26096073, 2015). "As amplification of MALAT1 was found in ESCC tissues, then we wondered how the amplification in tumor tissues occurred." (PMID 25613496, 2015). "MALAT1 was found positively correlated with Gleason score, the level of prostate specific antigen (PSA), tumor stage and castration resistance in PCa." (PMID 26516927, 2015). "To further verify the role of MALAT1 and to determine the therapeutic potential of targeting MALAT1 in OSCC, we established xenograft tumor models using Tscca cell lines." (PMID 26522444, 2015). "We found 5 of these CARs/lincRNAs (MALAT1, MEG3, NEAT1, NBPF1, and AC058791.1) significantly downregulated in primary tumor samples compared to normal tissue." (PMID 25264628, 2014). "PAICS, an enzyme required for de novo purine biosynthesis, the long non-coding RNA MALAT1 and the MAST2 kinase are overexpressed in certain tumor entities and capable of suppressing apoptosis in human cells." (PMID 23717670, 2013). "Our Oncomine database searches revealed an overexpression of PAICS, MALAT1 and MAST2 mRNA in various tumor entities." (PMID 23717670, 2013). "On the other hand, activation of genes involved in cell survival, angiogenesis and tumor progression, such as VEGF, S100P, MALAT-1 and different stress response genes, raises questions." (PMID 17880733, 2007). "Mechanistically, RNA-based therapeutics MALAT1 activates the EZH2/STAT3 axis, modulates the HIF-1α-KDM3A pathway under hypoxia, interacts with FAM46C to drive migration, and sponges tumor-suppressive miRNAs such as miR-125b, miR-1271-5p, miR-509-5p, miR-188-5p, and miR-15a/16." (PMID 41596492, 2026). "H19, NEAT1, and MALAT1 showed significantly altered expression in tumor tissue, as well as non-tumor tissue before and after nCRT." (PMID 41751809, 2026).
tumor (continued). "For instance, upregulated long non-coding RNAs (lncRNAs), such as MALAT1 and circular RNAs (circRNA), like circ_0007841 (acting via miR-129-5p/JAG1), alter transcriptional networks, enhance immune escape mediated by the tumor microenvironment (TME), and foster therapy resistance." (PMID 41596492, 2026). "Significant differences were observed in the MALAT1 expression of the A431 tumor when compared to peritumor tissue (P < 0.001) and other normal tissues (P < 0.001, bone P < 0.01)." (PMID 40597438, 2025). "In addition, MALAT1 binds to miR-202, relieving the inhibition of MMP2/MMP9, which further supports the remodeling of the tumor microenvironment." (PMID 40723840, 2025). "Authors showed that silencing MALAT1 or ADAM10 could prevent MICA/B release, enhancing NK cell-mediated clearance of senescent tumor cells." (PMID 40496868, 2025). "MALAT1, a well-known tumor-promoting lncRNA, competitively binds to microRNAs (miRNAs) such as miRNA-101 to relieve the inhibition of the PAM signaling pathway, thereby promoting tumor cell proliferation and migration." (PMID 40041495, 2025). "In addition to miRNA, several lncRNAs, including HOTAIR, MALAT1, TUG1, and NEAT1, play crucial roles in regulating gene expression and significantly impact tumor progression." (PMID 40806675, 2025). "Cy5.5-MALAT1-ASO was predominantly taken by tumors at 48 h post injection and the addition of unlabeled MALAT1 ASO for blocking resulted in a significant decrease in fluorescence intensity in tumor tissues." (PMID 40597438, 2025). "A study of 20 randomly selected pairs of BC samples found that the expression of MALAT1 in tumor tissues was significantly higher than that in normal non-cancerous tissues." (PMID 40223929, 2025). "Moreover, the overall m6A level and its related METTL3, METTL14, and WTAP protein levels, as well as cytoplasmic MALAT1-exporting IGF2BP3 and its distribution in xenograft tumor tissues, were increased in the HBx group." (PMID 40860202, 2025). "Preclinical studies have demonstrated that silencing of MALAT1, HOTAIR, or SAMMSON using antisense oligonucleotides (ASOs) or gapmeRs dramatically reduces intratumoral vessel density and tumour growth and shows synergistic effects with BRAF/MEK inhibitors and bevacizumab." (PMID 41463281, 2025). "We found a significant correlation between MALAT1 expression levels and distant metastasis but no such correlation with other pathological factors such as tumor staging, lymph node metastasis, and tissue differentiation." (PMID 39471147, 2024). "The knockout of the MALAT1 gene in esophageal cancer cells (ESCCs) resulted in an increased number of cells in the G2/M phase and activation of the ATM-CHK2 pathway, the role of which is to prevent too-rapid tumor growth by inhibiting the G2/M phase." (PMID 38674413, 2024). "However, MALAT1 knockdown in DLBCL cell lines induced cell cycle arrest, decreased proliferation and migration of tumor cells, and promoted apoptosis." (PMID 38255996, 2024). "Increased expression of MALAT1 in the course of hilar cholangiocarcinoma (HCCA) was correlated with the pathological T stage of the tumor (according to the TNM classification), nerve invasion, and increased tumor area." (PMID 38674413, 2024). "These associations remained statistically significant even after being adjusted for tumor metastasis and patients’ age, suggesting that TCF12 could collaborate with MALAT1 to exacerbate CRC patients’ OS independently of patients’ age and tumor metastasis." (PMID 39768127, 2024). "High MALAT1 expression may be employed as a marker of advanced CRC and recurrence because it was directly correlated with the CRC pathology stage and tumor recurrence." (PMID 38294554, 2024). "MALAT1 is a key regulator in HCC and is closely related to tumor metastasis and recurrence." (PMID 38739668, 2024).
tumor (continued). "Highly efficient knockdown of MALAT1 (using zinc finger nuclease-based technology) in extensive organization tumor cells confirmed that MALAT1 promotes in vitro and in vivo metastasis without affecting tumor cell proliferation." (PMID 38585701, 2024). "MALAT1, as a splicing factor proline-and glutamine-rich (SFPQ) bound competitor, will accelerate the dissociation of PTBP2 from the SFPQ/PTBP2 complex, enhance the function of PTBP2, and promote the proliferation and migration of tumor cells." (PMID 36829256, 2023). "Expression of MALAT1, in relation to the size of the tumor, was not statistically significant either (p = 0.13)." (PMID 38203269, 2023). "In total, five populations were designated tumour clusters, which had various features: (TumourC0) CD74 and APOD; (TumourC1) IF16, JUN and HSPA1A; (TumourC2) S100B and SCRG1; (TumourC3) NEAT1 and MALAT1; and (TumourC4) WFDC2 and RNASE1 (HLA‐DRA, CD68, CD3D, CD3E)." (PMID 37784253, 2023). "GSC transfer lncRNA MALAT1 (nuclear-enriched abundant transcript 2, NEAT2) cells into microglia in an EVs manner and regulate inflammatory responses mediated by the miR-129-5p and HMGB1 cascade to achieve pro-tumor effects." (PMID 37700840, 2023). "Notably, MALAT1 recruits EZH2 (Enhancer of zeste homolog 2) and increases H3K27 trimethylation level at target loci to inhibit gene expression, thereby facilitates tumor malignancy." (PMID 36813772, 2023). "In our investigation, tumor tissues had much higher levels of MALAT1 expression than the adjacent non-cancerous tissues." (PMID 37244966, 2023). "Tumor-cell-specific deMuts included many COSMIC genes, such as VEGFA, NEAT1, MALAT1, HILPDA, etc.." (PMID 37433798, 2023). "In a lung metastasis model, 786-O-EVs promoted tumor growth and RCC lung metastasis, which could be mitigated by inhibiting MALAT-1." (PMID 38124072, 2023). "Some of them are under investigation such as circulating tumor cells (CTCs), PTEN, androgen receptor variants, long non-coding RNAs such as HOX transcript antisense intergenic RNA, SChLAP1 and MaLAT-1, and several miRNAs such as miRNA-141 and miRNA-301a." (PMID 37740236, 2023). "Then, we collected the xenografts and inguinal lymph nodes and found that the tumor weight of xenografts treated with MALAT1 siRNAs was much lighter than that of negative control." (PMID 36813772, 2023). "Furthermore, to investigate the effect of coinhibition of MALAT1 and PARP in tumor xenografts, we performed IHC staining for the cell proliferative marker Ki-67." (PMID 37812088, 2023). "One possible explanation for this observation is that the observed correlation could reflect a more complex interplay between MALAT1 and NRAS expression in the tumor microenvironment, which cannot be recapitulated in vitro using cell lines." (PMID 37235843, 2023). "We further explored the methylation of lncRNAs associated with tumor progression through bioinformatics analysis and IGV, and found there was no significant change between CR and relapse samples, such as XIST, MALAT1 and so on (data not shown)." (PMID 37402730, 2023). "Notably, lncRNAs play a role in tumor suppression (e.g., GAS5, LINC-PINT, MEG3) and tumorigenesis (e.g., HOTAIR, RCAR4, MALAT1)." (PMID 35546353, 2022). "The results demonstrated that the expression of anti‐tumour lncRNAs DICER‐AS1, TUG1, GAS5 and LINC01121 was significantly increased by 50 μM resveratrol in combination with H19 knockdown, while expression of MALAT1 in cells was significantly downregulated by the combined treatment." (PMID 35166018, 2022). "MALAT1 through suppression of miR-324-3p and stimulation of ADAM17 (as a target of miR-324-3p) could reduce the Ox-sensitivity of CRC cells in xenograft tumor mice treated with Ox." (PMID 35305641, 2022). "Due to laboratory conditions, animal models of tumor metastasis were not used to detect the effect of the JMJD2C/MALAT1/miR-503-5p/SEPT2 signal axis on NSCLC in vivo." (PMID 35046387, 2022).
tumor (continued). "The performance of MALAT1 alone was not inferior to that of clinical stage and HBsAg in the prediction of progression, or from that of tumor size and HBsAg in the prediction of survival when data were censored at > 40 months." (PMID 36685103, 2022). "Next-generation sequencing as well as microarray analysis have identified recurrent deregulated lncRNAs (e.g., MALAT1, H19, HOTAIR, ANRIL) across different cancer types that affect tumor-driving processes including proliferation, survival, migration or genomic stability." (PMID 35454868, 2022). "Further, upregulated MALAT1 promotes the EMT process of CRC cells and tumor metastasis." (PMID 35922756, 2022). "In addition, we noted that in tumor samples the expression level of MEG3, TIMP, DAPK1 and SOX1 was lower, while the expression of MLH1 and MALAT1 was higher in comparison to the normal samples." (PMID 35682732, 2022). "Thus, we noticed that overexpression of MALAT1 and BACH1 was detected in TNBC with poor prognostic variables such as tumor size, nodal metastasis, and advanced tumor stage." (PMID 35096427, 2022). "LncRNAs such as MALAT1, XIST and NORAD have been proven to be biomarkers for human tumor prognosis." (PMID 35183058, 2022). "Taken together, our results highlight a complex interplay involving different species of RNAs, in which miR-378a-3p displays a tumor-suppressor function in CRC-SCs by modulating lncRNAs NEAT1 and MALAT1 that are critical for CRC cell growth and metastatization." (PMID 35814429, 2022). "Moreover, si-MALAT1 was reported to reduce OCT4 expression in lung adenocarcinoma and suppress tumour growth, metabolism and stemness." (PMID 35907897, 2022). "The lncRNA MALAT1 was highly expressed in NSCLC cell exosomes and tissues, and its knockdown induced apoptosis by regulating Bcl-2/Bax protein expression and exerted anti-tumour effects by targeting EEF2 via miR-515-5p." (PMID 35379783, 2022). "Together, our data showed that miR-378a-3p may exert its tumor suppressor function modulating NEAT1 and MALAT1 lncRNA expression, though a weaker tumorigenic inhibition was observed in miR-378 restoration experiments compared to knockdown experiments." (PMID 35814429, 2022). "In addition, lincRNA-p21 has been described as a tumor suppressor, while HOTAIR, MALAT-1, H19, PVT1, ANRIL, and GIHCG, have been characterized as oncogenic lncRNAs." (PMID 36360316, 2022). "The upregulation of tumour tissue-derived lncRNAs (HOTAIR, MALAT1, SHNG1 and SHNG6) might be adverse prognostic factors of GC." (PMID 36310592, 2022). "With the deepening of research, further understanding of ginkgolic acid inhibition of lncRNA MALAT1/JAK2 axis on the biological function of OCa cells and its role in the process of tumor development will be more conducive to the diagnosis, treatment, and prognosis assessment of OCa." (PMID 34987594, 2021). "MALAT1 can also competitively bind to miR-181a-5p, which prevents miR-181a-5p from binding to AKT3 mRNA, thereby up-regulating the level of AKT3 protein and ultimately promoting tumor growth in GC." (PMID 34356052, 2021). "The juggling tumor suppressor ncRNA category includes miR-16, miR-34a, miR-142-3p, lncRNA CCAT1, lncRNA COX2, lncRNA GAS5, and lncRNA NIFK-AS1 while the category of juggling oncogene includes miR-503 and lncRNA MALAT1." (PMID 33522932, 2021). "Another study reported similar results, that MALAT1 expression levels were significantly higher in tumor tissues as compared with adjacent noncancerous tissues." (PMID 34012919, 2021). "Although the combination of MALAT1 and PVT1 with other tumor markers may improve the early CRC diagnosis, this needs further investigation." (PMID 34200314, 2021). "Association between the expression of EMT-related genes (specifically MMP2 and MMP9) and lncRNAs MALAT1 (study performed on OC tumor tissue samples (n = 64) and reference tissue (n = 30)) and TP73-AS1 (study done on 60 pairs of OC tumor/control tissue) was observed." (PMID 33921525, 2021).
tumor (continued). "The expression of MALAT1, miR-655-3p, and ATAD2 in tumor tissue of nude mice were also analyzed." (PMID 34222668, 2021). "Metastasis-associated lung adenocarcinoma transcript 1 (MALAT1) is an oncogenic lncRNA that is highly expressed in GBM and that drives tumorigenesis and tumor propagation through regulations of miR-129, SOX2, and non-canonical Wnt signaling." (PMID 34361090, 2021). "To determine whether the PCA3 and MALAT1 scores were correlated with the tumor grade of PCa, we evaluated the PCA3 and MALAT1 scores in the clinically significant PCa (GS ≥ 7) with those in nonaggressive disease (PCa with GS6 and benign disease)." (PMID 34439239, 2021). "MALAT1 depletion inhibited cell proliferation, metastasis, and epithelial–mesenchymal transition (EMT), but promoted apoptosis in vitro and blocked xenograft tumor growth in vivo." (PMID 34222668, 2021). "MALAT1 upregulation correlates with tumor cell proliferation, invasion and chemoresistance through Nova1 regulation." (PMID 34425750, 2021). "In addition, there was a positive correlation between MALAT1 and the clinicopathological parameters in CRC patients e.g., tumor stage (r = 0.3340, p = 0.0231), lymph node status (r = 0.3600, p = 0.019) and metastasis (r = 0.3062 p = 0.0385), respectively." (PMID 34200314, 2021). "MALAT1 also primarily functions as a competitive endogenous lncRNA in CRC, which targets and regulates the sponging of miR-126-5p, miR-663a, miR-15, and other microRNAs to exhibit a tumor suppressor effect." (PMID 34938735, 2021). "Serum small EV‐derived MALAT1, DLEU2, HOTTIP, and SNHG1 were significantly highly expressed in patients with HCC and showed good to excellent discriminating capacity that was significantly higher than that of the traditional tumor marker AFP." (PMID 34185961, 2021). "Exosomes containing MALAT1 are released into the tumor microenvironment, inhibiting and depleting YAP1, activating ERK1/2 signal transduction, and enhancing the expression of MMP2 and MMP9, thereby promoting tumor invasion and metastasis." (PMID 35145971, 2021). "Moreover, tissue expression levels of MALAT1 positively correlated with tumor grade according to the world health organization (WHO) classification and tumor size." (PMID 34322395, 2021). "Furthermore, in xenograft tumor tissues, DANCR knockdown also dramatically impaired MALAT1 expression." (PMID 33414433, 2021). "In addition, exosomal MALAT1, derived from NSCLC patients, accelerates tumor migration and proliferation by suppressing apoptosis in lung cancer cell lines." (PMID 34830787, 2021). "Besides, associations between these lncRNAs and CRC clinicopathological parameters were found, such as stage, nodal and distant metastases, suggesting that MALAT1 and PVT1 play a crucial role in directly contributing to tumor progression." (PMID 34200314, 2021). "A recent study found that lncRNA MALAT1 was overexpressed in LSCC tissues and highly correlated with the 5‐year survival of patients; it triggers the resistance of LSCC to chemotherapy drugs by promoting metastasis and inhibiting tumor cell apoptosis." (PMID 34048096, 2021). "Moreover, the upregulated expression of several lncRNAs, such as LINC00152, MALAT1, PVT1, UCA1, etc are also correlated with poor prognosis, tumor progression, lymph node invasion, and TNM stage advancement." (PMID 34944491, 2021). "LncRNAs such as HOTAIR, MALAT1, ANRIL and SRA are up-regulated in tumors and play the role of oncogenes, while MEG3, GASS and LncRNA-p21 are down-regulated in tumors and play a role of tumor suppressors." (PMID 34616746, 2021). "In addition, PCR assays revealed that MALAT1 gene expression was downregulated by BA both in HCC cells and tumor tissue." (PMID 33135336, 2020). "In thyroid cancer, lncRNA MALAT1-mediated fibroblast growth factor-2 (FGF2) secretion from TAMs depresses release of inflammatory cytokines, induces vasculature formation and accelerates proliferation, invasion and migration of tumor cells." (PMID 33148302, 2020).